MIR4435-2HG (MIR4435-2 host gene)
Synonyms: LINC00978; AGD2; AK001796; lncRNA-AWPPH; MORRBID; MIR4435-1HG
Gene: Long non-coding RNA gene on chromosome 2 (111,006,015 to 111,523,376, reverse strand). Ensembl gene ENSG00000172965.
Diseases named in the same sentence as MIR4435-2HG in open-access papers:
MIR4435-2HG is named in the same sentence as 15 diseases in open-access papers, as found by Europe PMC text mining. Sharing a sentence is not in itself a finding about the gene and the disease. The quoted sentences say what the papers report.
breast carcinoma (5 papers, 2016 to 2022). "Recently, LINC00978 (also known as MIR4435-2HG, AGD2, or MORRBID) was identified as a novel lncRNA that promotes lung cancer growth and acts as a biomarker for gastric and breast cancer patients." (PMID 32077915, 2020). "MIR4435-2HG, also known as AGD2, MORRBID, LINC00978, MIR4435-1HG, lncRNA-AWPPH, has been regarded as a new oncogenic lncRNA in many types of cancer, like breast cancer and bladder cancer." (PMID 30972258, 2019).
hepatocellular carcinoma (3 papers, 2020 to 2022). A malignant tumor that arises from hepatocytes. "The lncRNA MIR4435-2HG (namely, lncRNA-AWPPH, MIR4435-1HG, LINC00978, MORRBID, and AGD2) was initially identified as a prognostic biomarker for hepatocellular carcinoma." (PMID 32154166, 2020).
tumor (9 papers, 2016 to 2023). "Among reproductive system cancers, MIR4435-2HG is highly expressed in tumor tissues and tumor cell lines of ovarian cancer, cervical cancer, and breast cancer." (PMID 35784328, 2022). "Conversely, LINC00978 (also known as miR4435‐2HG) was mainly located in the CAC tumour stroma and played as a tumour suppressor molecule by remodelling the immune microenvironment." (PMID 37138536, 2023).
cancer (5 papers, 2019 to 2022). A tumor composed of atypical neoplastic, often pleomorphic cells that invade other tissues. "AWPPH, also well-known as AK001796, MIR4435-2HG, LINC00978 and other names, was localized at 2q13 and found to be dysregulated in many human cancers." (PMID 34042153, 2021).
MIR4435-2HG also shares sentences with these, for which no sentence is quoted: bladder cancer (3 papers); gastric cancer (3); hypospadias (2); lung carcinoma (2); colorectal cancer (1); hypereosinophilic syndrome (1); liver cancer (1); lymph node metastasis (1); melanoma (1); metabolic disorders (1); non-small cell lung carcinoma (1).